NCK2 (NCK adaptor protein 2)
Diseases named in the same sentence as NCK2 in open-access papers (continued):
Sharing a sentence is not in itself a finding about the gene and the disease.
Azoospermia (1 paper, 2023). Absence of any measurable level of sperm,whereby spermatozoa cannot be observed even after centrifugation of the semen pellet. "Collectively, these results implicate that OIP5 interacts with NCK2 to modulate human SSC self-renewal and apoptosis via cell cyclins and cell cycle progression and that its mutation and/or lower expression is correlated with azoospermia." (PMID 37292517, 2023).
colon cancer (1 paper, 2011). "In contrast, Nck2 that was below detection level in CT36 and CT51, was distinctly detected in CT26, revealing increased expression of Nck2 in aggressive metastatic colon cancer cells." (PMID 21992144, 2011).
glaucoma (1 paper, 2013). Increased pressure in the eyeball due to obstruction of the outflow of aqueous humor. "This localization makes it highly conceivable that the Hk2 gene products could each play a role in glaucoma, and there is possibility that Nck2 could have relationship with glaucoma." (PMID 23349798, 2013).
Hepatic fibrosis (1 paper, 2023). The presence of excessive fibrous connective tissue in the liver. "The intestinal microbiome characteristics of hepatic fibrosis patients that enhance oxidative stress and an inflammatory environment are related to the NCK2 single nucleotide polymorphisms RS3769502 and RS7573751." (PMID 36761433, 2023).
insulinoma (1 paper, 2022). "Interestingly, the SH2 domain of Nck1 and Nck2 has been found to mediate the interaction with phospho-PERK at Tyr-561 (Y561) in mouse insulinoma MIN6 cells and limit PERK activation." (PMID 35902806, 2022).
metastatic cancer (1 paper, 2011). A carcinoma which has spread from the original site of growth to another anatomic site. "Together these results provide the first evidence that the expression of Nck2 is increased in metastatic cancer cells of various origins and argue for a role of Nck2 in cancer progression." (PMID 21992144, 2011). "We found that expression of Nck2 is consistently increased in various metastatic cancer cell lines compared with primary counterparts." (PMID 21992144, 2011). "Given other common metastatic cancer cell lines also overexpress Nck2, a general paradigm could make Nck2 a potential molecular marker of cancer progression and a novel target for anti-cancer drug therapy." (PMID 21992144, 2011).
nevus (1 paper, 2017). Nevus (or naevus, plural nevi or naevi, from nævus, Latin for "birthmark") is the medical term for sharply circumscribed[1] and chronic lesions of the skin or mucosa. "Finally, in other studies up-regulation of NCK2 was present in melanoma tumor samples from metastasis compared to nevocellular nevus lesions by semi-quantitative RT–PCR and custom array analysis, suggesting a role of NCK2 in melanocytic tumor progression." (PMID 29088810, 2017).
nicotine dependence (1 paper, 2013). Physical and psychological dependence on nicotine. "For the addiction of the other five substances in African-origin men, nicotine dependence had the most significant association with the NCK2 gene (P = 9.56 × 10−3)." (PMID 23533358, 2013). "The association between NCK2 and nicotine dependence has been suggested in humans." (PMID 23533358, 2013).
cancer (6 papers, 2011 to 2025). A tumor composed of atypical neoplastic, often pleomorphic cells that invade other tissues. "Nck1 and its paralog Nck2 are elevated in many cancers, and their overexpression promotes malignant transformation." (PMID 25137142, 2014). "In fact, we found higher levels of Nck2 expression in metastatic compared to non metastatic cell lines in three different types of cancer." (PMID 21992144, 2011). "Expression of Nck1 and Nck2 proteins in various cancer cell lines at different stages of progression were analyzed by western blots." (PMID 21992144, 2011). "Previous studies on NCK2 in cancer are fewer still need to be further explored." (PMID 40438322, 2025). "Alternatively, increased expression of Nck2 could passively destroy proper stoichiometry of molecular complexes and in this manner, indirectly contributes to cancer progression by altering signaling pathways regulating the actin cytoskeleton network supporting cell migration." (PMID 21992144, 2011). "NCK2 is a hinge protein containing the -SH2 and -SH3 structural domains, which has been found to promote extracellular matrix degradation and cancer invasion." (PMID 40438322, 2025). "Indeed, previous studies by us and others have shown that PINCH-1 can interact with multiple signaling proteins including ILK 37, Nck-2 60, RSU-1 61, 62, EPLIN 50, myoferlin 53 and Notch-2 55, which may also contribute to the regulation of cancer cell proliferation and survival." (PMID 35401828, 2022).
tumor (5 papers, 2011 to 2025). "The NCK2 also showed a higher expression level in CM tumor tissue in both Talantov (P < 0.001) and Riker studies that included 14 CM tumor tissues and four normal skins (P = 0.023)." (PMID 29088810, 2017).
infection (2 papers, 2007 to 2022). The state of being infected such as from the introduction of a foreign agent such as serum, vaccine, antigenic substance or organism. "In order to elucidate the function of TccP2, we carried out infections of Nck1–/Nck2– fibroblast cell lines with EPEC 1 E2348/69 expressing tccP2_B171 (pICC365)." (PMID 17526832, 2007). "Accordingly, we compared the ability of EPEC 2, EPEC 1 and EHEC O157 : H7 to induce actin-pedestal assembly during infection of Nck1−/Nck2− and Nck1+/Nck2+ fibroblasts." (PMID 17526832, 2007). "Phalloidin staining and quantification of the efficiency of pedestal formation revealed that EDL933 was able to induce actin accretion during infection of an Nck1−/Nck2− fibroblast cell line, at a similar efficiency to infection of a control Nck1+/Nck2+ fibroblast cell line." (PMID 17526832, 2007). "(B) Left - The graph shows quantification of GFP-Nck:RFP-A3 fluorescence intensity ratio on virus particles in live mouse embryonic fibroblasts (MEFs) lacking both Nck1 and Nck2 and stably expressing GFP-Nck1 at 16 hr post-infection." (PMID 35796545, 2022).
retinopathies (1 paper, 2018). "Loss of Nck1 and Nck2 in mural cells prevents NVT formation and vascular leakage and promotes revascularization, suggesting PDGFRβ-Y1009/NCK signaling as a potential target for the treatment of retinopathies." (PMID 30150707, 2018).
NCK2 also shares sentences with these, for which no sentence is quoted: celiac disease (2 papers); alcohol dependence (1); amyotrophic lateral sclerosis (1); bladder cancer (1); central obesity (1); cholangiocarcinoma (1); cocaine dependence (1); kidney cancer (1); lung squamous cell carcinoma (1); male infertility (1); opioid use disorder (1); rheumatoid arthritis (1).